DCX (doublecortin)
Diseases named in the same sentence as DCX in open-access papers (continued):
Sharing a sentence is not in itself a finding about the gene and the disease.
ischemia (25 papers, 2012 to 2025). A hypoperfusion of the BLOOD through an organ or tissue caused by a PATHOLOGIC CONSTRICTION or obstruction of its BLOOD VESSELS, or an absence of BLOOD CIRCULATION. "Nevertheless, in sham-operated animals the number of DCX+/BrdU+ cells was much lower than in those that underwent experimental ischemia." (PMID 38674304, 2024). "Taken together, these findings suggest that locally activated nestin+ iNSPCs generate DCX+ cells following ischemia, in accord with previous studies." (PMID 38534363, 2024). "In the present study, we performed immunohistochemical staining for Ki67 and DCX to confirm the effect of cuprizone on ischemia-induced hippocampal neurogenesis." (PMID 32531881, 2020). "The present study measured the BrdU+/Nestin+ cells and BrdU+/DCX+ cells related to ET-1-induced ischemia in the SVZ and found that the proliferation of NPCs can be enhanced by LCN DBS combined with pasta reaching training, initiated at week 2 poststroke." (PMID 33024145, 2020). "Herein, the number of BrdU+ and DCX+ NSPCs was evaluated between cortex and striatum at penumbra after ischemia as shown in schematic image." (PMID 31607868, 2019). "Our PT-induced ischemia did activate the astrocytes and microglia, which was companied by a delayed occurrence of DCX+ cells in the striatum." (PMID 30524246, 2018). "At day 7 post-ischemia, when DCX+ neurons were first observed after the injury, we focused on comparison of transcriptions of the genes in the striatum of both GFAP-CreER:Rbp-Jfl/fl mice and the Rbp-Jfl/fl." (PMID 30524246, 2018). "The number of DCX-positive neurons reached the peak level at day 7, but they were still observed at day 28 post-ischemia." (PMID 30524246, 2018). "Further data showed that the number of DCX+/BrdU+ NPCs and NeuN+/BrdU+ newborn neurons in the perifocal area of ischemia were significantly increased in all therapeutic groups compared to the PBS group." (PMID 29751775, 2018). "Our findings provide evidence that in a murine model of focal ischemia, the majority of DCX+ cells in the perilesional zone are of glial nature." (PMID 25881110, 2015). "It is more likely that local residing cells (e.g. neuronal or glial cells) are stimulated to express DCX following ischemia." (PMID 25881110, 2015). "Further studies are required to elucidate the functional role of the distinct DCX+ cells following ischemia." (PMID 25881110, 2015). "It was reported that BrdU-positive cells expressing DCX reached their maximum number between the 4th and 7th day after ischemia; thereafter, DCX expression rapidly declined, and then expression of NeuN slowly increased." (PMID 25388889, 2014). "In accordance with our results, decreased DCX +, BrdU +, or BrdU + /DCX + staining has been reported following several surgery models, such as ischemia–reperfusion of the upper mesenteric artery, ischemia–reperfusion of the left coronary artery, and carotid exposure." (PMID 37798730, 2023). "In a transient ischemic stroke study, a low dose of C3aR antagonist (1 mg/kg) within 3 days after ischemia increased DCX+ neuroblast proliferation in the subventricular zone at 7 days post-ischemia, while a high dose of C3aR antagonist (40 mg/kg) suppressed neural progenitor cell proliferation." (PMID 31011487, 2019). "To test whether the focal ischemia is able to trigger appearance of new-born neurons in the injured striatum, we examined DCX-expressing cells." (PMID 30524246, 2018). "In our study, PT-induced ischemia would break the homoeostasis, activating the astrocytes and promoting the neurogenic program of DCX+ cells, which may be paralleled by complicated changes in transcriptional network." (PMID 30524246, 2018). "In our study, we found that focal striatal ischemia could also elicit the occurrence of DCX+ cells in adult mice, although it was a delayed process compared to glial cells." (PMID 30524246, 2018).
ischemia (continued). "Interestingly, BrdU- and DCX-positive cells in the DG were decreased after focal ischemia, compared to the sham-operated rats (*P < 0.05), which was reversed after E2 administration (*P < 0.05)." (PMID 24307996, 2013). "DCX+ neural progenitor cells move along the perfused vessels, indicating that enhanced angiogenesis may facilitate the neurogenesis and reconstruction of neuronal network, as well as the recovery of sensorimotor functions after ischemia in aged brain." (PMID 28966799, 2017). "Confocal images show that BrdU-positive cells expressed DCX, suggesting that these BrdU-positive cells were proliferative neuronal progenitor cells, and double-labeled cells in E2-treated group were significantly increased compared to vehicle-treated group after ischemia (**P < 0.001)." (PMID 24307996, 2013). "After ischemia, some EGFP+/DCX+ cells displayed Na+ currents with a significantly higher CD and markedly different kinetics when compared to polydendrocytes, together with high membrane resistance, which is a typical feature of immature neuroblasts." (PMID 22590616, 2012). "The number of DCX-positive cells increased after hypoxia (the contralateral hemisphere is subjected to hypoxia, but not ischemia) and DCX counts revealed 13.6±0.6 cells/mm in the vehicle-treated group vs. 16.9±0.6 cells/mm in the lithium treatment group 12 weeks after HI (p = 0.0004)." (PMID 25211332, 2014). "However, reduced brain weight and delayed gyrification on fetal MRI in CHD53 and reduced doublecortin+ neuroblasts, cortical growth, and NeuN/calretinin+ interneurons, but not NeuN/Tbr1+ neurons, in models of perinatal ischemia, support an additional developmental neuronal‐migratory defect." (PMID 40299318, 2025). "However, sovateltide treatment induced expression of DCX, HuC/HuD and NeuroD1 in the right ischemic cerebral hemispheres of rat brains at 24 h post MCAO, which suggests a role of sovateltide in maintenance and differentiation of NPCs to generate new neural cells after acute ischemia." (PMID 32728189, 2020).
Anxiety (21 papers, 2012 to 2025). Intense feelings of nervousness, tension, or panic often arise in response to interpersonal stresses. "A reduction in neurons (i.e., doublecortin positive cells; DCX+) is associated with stress-related anxiety and depressive behavior; a return to baseline DCX+ cell number results in normalization of anxiety- and depressive-like behaviors." (PMID 29487509, 2018). "We suggest induced reduction in DCX+ cells at the time of behavioral testing is associated with stress-induced anxiety and depressive-like behavior, while recovery of DCX+ cell number corresponds to normalization of these behaviors." (PMID 26795203, 2016). "PARP-1 knock-out mice showed not only a high impact on NSC survival, DCX+ cells, and low neuronal differentiation that is associated with diminished social interaction but also with symptoms described as “schizophrenia-like behavioral deficits” that include hyperactivity and anxiety." (PMID 36407114, 2022). "Given the involvement of the ventral hippocampus in anxiety-like behavior, we next assessed the association between latency to enter the center of the open-field during the habituation phase, and expression of DCX in the dorsal and ventral hippocampal dentate gyrus of adult rats (P220)." (PMID 25729346, 2015). "Here, we aimed to determine the effects of calcium and/or vitamin D supplement on the anxiety- and memory-related behaviors and the expression of doublecortin (DCX), an indirect proxy indicator of hippocampal neurogenesis." (PMID 37566598, 2023). "An increase in DCX expression in the hippocampus was probably a mechanism to help protect brain against anxiety and to improve the hippocampus-dependent cognitive function." (PMID 37566598, 2023). "The results showed that TAM led to a significant decrease of DCX-positive cells and an early onset of anxiety at 10 dpi as compared with those TAM-treated WT mice." (PMID 30197587, 2018). "Here we show that induced, transgenic-mediated, transient reduction in DCX+ neuroblasts/immature neurons resulted in stress-induced anxiety and depressive-like behavior." (PMID 26795203, 2016). "In addition, study in mice revealed that supplementation of 6′-SL or 3′-SL can release anxiety during stressor tests, and prevent the gut dysbiosis resulting from stress, and help to maintaine normal numbers of doublecortin (DCX) + immature neurons." (PMID 34859034, 2021). "NU9056 remarkably improved the survival rate of LPS-stimulated mice, relieved cognitive dysfunction, anxiety, and depression, reduced DCX expression, hindered abnormal activation of microglia, reduced neuroinflammation, protected BBB function, and affected the composition of the gut microbiota." (PMID 34327209, 2021). "Similarly, AIE treatment with i.p injection of ethanol has been found to decrease adult hippocampal Ki67+ and DCX+IR while increasing HDAC activity and decreasing BDNF in association with increased anxiety." (PMID 28855864, 2017). "Loss of DCX+ neurons was associated with age-independent altered stress coping without a concomitant change in anxiety-related behavior, tallying with previous assertions that adult neurogenesis is necessary to buffer responses to more severe stress exposure." (PMID 26617501, 2015). "In both studies, BCI-838 treatment increased brain levels of markers of neurogenesis (BrdU, DCX, PCNA), reduced anxiety-related behaviors, and reversed learning behavior deficits." (PMID 39081972, 2023). "Curiously, when the investigators eliminated neurogenesis (DCX+ cells) in adolescence, there were no changes in memory and anxiety tests, but social exploration was severely affected." (PMID 36407114, 2022). "Furthermore, Nrf2 knockdown by a short hairpin RNA affected anxiety-like behaviors and expression of neuroprotective markers (BDNF, DCX) in a manner similar to ESPS alone and dampened the neuroprotective effects of EA pretreatment." (PMID 31293390, 2019).
Anxiety (continued). "In our transient TAM-induced reduction in DCX+ cell number results in only stress-induced anxiety in the NIH not baseline anxiety tests." (PMID 26795203, 2016). "While our Cre+DTA+ mice have transiently fewer DCX+ cell number and display depressive-like behaviors, they do not display baseline anxiety-like behavior in the L/D, OF, or EPM tests (data not shown) at any time point examined." (PMID 26795203, 2016). "Fuss and co-workers (2010) observed a significant negative correlation between anxiety and neurogenesis after 6 weeks running; nevertheless, this was with doublecortin, a marker of newly born cells that have already differentiated into neurons." (PMID 22682077, 2012). "However, at a later time point when DCX+ cell number normalized, stress-induced anxiety and depressive-like behavior were no longer evident." (PMID 26795203, 2016).
glioma (21 papers, 2008 to 2025). A benign or malignant brain and spinal cord tumor that arises from glial cells (astrocytes, oligodendrocytes, ependymal cells). "As a microtubule-associated protein, it is plausible that the function of DCX extends beyond regulating glioma cell proliferation potentially contributing to the mechanisms of cell death." (PMID 39719558, 2024). "Interfering with microtubule-associated protein expression can inhibit glioma cells growth and invasion, but the effect of DCX knockdown in glioma is totally unexplored." (PMID 39719558, 2024). "Other authors demonstrated a very low DCX expression in glioma and that a forced expression causes apoptosis and inhibits invasion." (PMID 31003495, 2019). "DCX is phosphorylated by CDK5 on Ser297 residue, likewise on Ser47 by PKA and MARK, both eventually led to reduction in DCX's binding affinity for MTs and in turn enhancing migration, a mechanism that can be implicated in the migration and invasion of highly invasive glioma." (PMID 28701917, 2017). "DCX has been identified as a marker of sensitivity and specificity in the invasive margins of glioma." (PMID 39719558, 2024). "As DCX is essential for cell proliferation and migration, interrupting DCX would offer the potential to alter the infiltrative nature of glioma." (PMID 39719558, 2024). "Emerging evidence suggests that DCX plays a role in regulating cellular processes in glioma, especially increased expression of DCX, which was correlated with glioma cell invasiveness." (PMID 39719558, 2024). "Previous studies have demonstrated that DCX has an essential oncogenic function in glioma pathogenesis." (PMID 39719558, 2024). "Targeting DCX presents a strategic approach to inhibit glioma growth and progression, highlighting its potential as a promising therapeutic target." (PMID 39719558, 2024). "Addressing the limitations identified in this study will be crucial for advancing the understanding of DCX’s role in glioma pathogenesis and its therapeutic significance." (PMID 39719558, 2024). "To investigate DCX’s effects on glioma cell survival and growth, we employed the CRISPR/Cas9 technique to stably knock down DCX in U251 cells." (PMID 39719558, 2024). "We also described a possible mechanistic function that DCX knockdown employs in glioma cells to trigger a cascade of events leading to apoptosis." (PMID 39719558, 2024). "Our previous study also demonstrated that overexpression of DCX and its nucleocytoplasmic transport via the RanGTPase signaling pathway enhanced glioma invasiveness and proliferation." (PMID 39719558, 2024). "Our finding suggests that DCX depletion reduces glioma cell proliferation and promotes mitochondria-dependent apoptosis by enhancing the chemo and radiotherapy response." (PMID 39719558, 2024). "Our results demonstrated that silencing DCX not only inhibited proliferation in U251 glioma cells but also reduced brain tumor growth in vivo." (PMID 39719558, 2024). "We showed that downregulation of DCX using a CRISPR/Cas9 technique impaired the proliferation of U251 human glioma cells and induced mitochondria-dependent apoptosis." (PMID 39719558, 2024). "While this study demonstrates the significant role of DCX knockdown in inhibiting glioma cell proliferation and promoting apoptosis, several limitations should be acknowledged." (PMID 39719558, 2024). "In summary, our findings suggest that the CRISPR/Cas9-mediated disruption of DCX expression represents a potential strategy for inhibiting glioma proliferation." (PMID 39719558, 2024). "In this study, we utilized CRISPR/Cas9 technology to knock down DCX in the human glioma cell line (U251)." (PMID 39719558, 2024). "Our study uncovers a novel role of Doublecortin (DCX) beyond its classical function in neuronal development, specifically in the regulation of mitochondria-dependent apoptosis in glioma." (PMID 39719558, 2024).
glioma (continued). "A more recent follow-up study evaluated the sensitivity and specificity of DCX immunostaining to detect infiltrating glioma cells." (PMID 34948016, 2021). "They found that cells with DCX overexpression had lower invasion abilities, thus, the authors concluded that DCX positive cells in glioma either infiltrate neuroblasts or pre-existing neuronal cells." (PMID 34948016, 2021). "DCX positive cells within glioma tumours, in their opinion, were either infiltrating neuroblasts or pre-existing neuronal cells." (PMID 34948016, 2021). "Since DCX nuclear accumulation only occurs in glioma cells, we investigated the effects of DCX nucleocytoplasmic transport on glioma progression." (PMID 32050972, 2020). "We have also identified here that DCX shuttles to the nucleus of glioma cells, and it requires specific residues between ser47 and tyr70 in a RanGTPase dependent manner." (PMID 32050972, 2020). "Here, we clarified DCX expression in gliomas and report a RanGTPase-dependent nuclear import of DCX in glioma cells via a bipartite classical nuclear localization signal (cNLS)." (PMID 32050972, 2020). "Stable cells expressing CRISPR-Cas9-induced DCX overexpression were utilized to probe the effects of high DCX expression on glioma cells." (PMID 32050972, 2020). "It is predictable that research on DCX and its pro-oncogenic functions will be further appreciated with a broad interest in its research with regards to glioma development." (PMID 32050972, 2020). "Next, C6 cells and GDCX-C6 cells were injected intracranially in BALB/c nude mice brain (n = 12; 6 × 105 cells per injection) to examine the influence of DCX in gliomas in vivo." (PMID 32050972, 2020). "All human glioma cell lines probed showed preferential DCX expression relative to the respective astrocytic cells." (PMID 32050972, 2020). "Together, these pathological and molecular criteria indicate that nuclear translocation of DCX is pivotal to the pro-oncogenic functions of DCX in gliomas." (PMID 32050972, 2020). "Based on the extensive study of DCX in neuronal development and its crucial roles in adult neurogenesis, this study opens a broader interest in possible exploitation of DCX functions in neurons by glioma communication systems." (PMID 32050972, 2020). "Given that DCX regulates neuroblast development during adult neurogenesis, we examined the relationship between high DCX expression and glioma progression." (PMID 32050972, 2020). "High expression and nuclear accumulation of DCX improve invasive glioma abilities in-vitro and in-vivo." (PMID 32050972, 2020). "Collectively, this study highlights a remarkable phenomenon in glioma, hence revealing potential glioma dependencies on DCX expression, which is amenable to targeted therapy." (PMID 32050972, 2020). "We probed DCX expression in different grades of glioma tissues and conventional cells via western blotting." (PMID 32050972, 2020). "Since the first report on DCX expression in gliomas, its functions in glioma development have remained exclusive." (PMID 32050972, 2020). "Doublecortin is expressed in both cytoplasmic and nuclear compartments of glioma cells, and its expression is consistent with glioma grades." (PMID 32050972, 2020). "These in vitro and in vivo functional studies indicate that DCX contributes to the development of invasive gliomas." (PMID 32050972, 2020). "In the present study, we further provide evidence on the expression of DCX in glioma cells and report a nexus between DCX expression and glioma development." (PMID 32050972, 2020). "For the first time, we report that DCX is expressed in the nucleus of glioma cells via the RanGTPase signaling, consequently promoting glioma progression." (PMID 32050972, 2020). "DCX is expressed in gliomas, and its contribution to the formation and migration of neuroblasts makes it susceptible to pro-oncogenic entities." (PMID 32050972, 2020).